ILF3-DT (ILF3 divergent transcript)
Synonyms: ILF3-AS1
Gene: Long non-coding RNA gene on chromosome 19 (10,651,859 to 10,653,879, reverse strand). Ensembl gene ENSG00000267100.
Diseases named in the same sentence as ILF3-DT in open-access papers:
ILF3-DT is named in the same sentence as 3 diseases in open-access papers, as found by Europe PMC text mining. Sharing a sentence is not in itself a finding about the gene and the disease.
ILF3-DT shares sentences with these, for which no sentence is quoted: epilepsy (1 paper); melanoma (1); osteosarcoma (1).